MIR5187 (microRNA 5187)
Synonyms: hsa-mir-5187; mir-5187
Gene: MicroRNA gene on chromosome 1 (161,227,186 to 161,227,261, forward strand). Ensembl gene ENSG00000284035.
Homologues: Orthologues: chimpanzee MIR5187 (100% identical).